CD68 (CD68 molecule)
Diseases named in the same sentence as CD68 in open-access papers (continued):
Sharing a sentence is not in itself a finding about the gene and the disease.
Obesity (continued). "In contrast, it did stain some CD68-positive macrophages forming CLSs or MGCs as well as some interstitial macrophages found among adipocytes in 16 of the 31 subjects with obesity, albeit with considerable variability in the degree of positivity." (PMID 38141849, 2024). "We find that STING+/CD68+ macrophages are increased in lung tissues in patients with obesity." (PMID 36782056, 2023). "Because macrophages are the main component in most cases of obesity-induced chronic inflammation, we performed IHC analysis using antibodies against CD68 and F4/80 to demonstrate that macrophages were highly associated with HFD-enhanced lung cancer progression." (PMID 37929799, 2023). "In addition, onions were found to be effective in suppressing the inflammatory response accompanying obesity by reducing the expression of pro‐inflammatory markers such as CD68, MCP‐1, and PPARγ in adipose tissue." (PMID 37576046, 2023). "Furthermore, changes in transcriptional factor cascades, such as increased expression of adipogenic genes (PPAR-γ, aFABP, lipogenic genes (FAS), and macrophage-specific markers (CD68, F4/80), have been reported in obesity-related studies." (PMID 36056976, 2022). "The highest protein levels of CD68 were observed in the eWAT of the HFD Inpp4b−/− group, suggesting that the INPP4B deficiency promotes the inflammatory response of adipose tissue in diet-induced obesity." (PMID 33772116, 2021). "Furthermore, EA ameliorated obesity-associated inflammatory responses through decreasing area neutrophil+, area CD11b+, area F4/80+, F4/80 mRNA, TNF-α mRNA, MCP-1 mRNA, CD68 mRNA, and IL-6 mRNA in adipose tissues." (PMID 35095910, 2021). "Furthermore, elevated expression of ICAM-1 has been described in the abdominal AT of mice with diet-induced obesity, and in the visceral AT of obese women, in correlation with the expression of the macrophage-related marker CD68 and with BMI." (PMID 31627295, 2019). "This was parallel to the normalization in the expression of the macrophage markers F480 and CD68 and of the pro‐inflammatory cytokines TNF‐α and IL‐1β, indicating that FGF21 expression counteracted the inflammation of WAT associated with obesity." (PMID 29987000, 2018). "Because HFD-induced obesity is associated with adipose tissue inflammation, it is not surprising that we noted elevated levels of Cd68 and Mcp-1 in high fat fed animals in the present study." (PMID 29562620, 2018). "In addition, dapagliflozin decreased the IF expression of the macrophage marker CD68 in WD-fed obesity mice." (PMID 29301371, 2018). "However, when we switched from BMI values to obesity phenotypes, SO patients’ population demonstrated statistically significant increase in aromatase and macrophage marker CD68 expression compared to MHO group." (PMID 27853670, 2016). "Again obesity aggravated the effect of aging on CD68 expression." (PMID 26604973, 2015). "However, compared to cachectic and normal-weight COPD patients, those with obesity had median values of adipose tissue expressions of CD68 higher by 240% and 89%, and of TNF-α by 88% and 109%, respectively." (PMID 21197447, 2010). "In addition, antibody neutralization of CD44 reduces obesity-induced adipose tissue inflammation, as demonstrated by decreased expression of immune cell markers (CD68, F4/80, CD3e, and CD19), proinflammatory cytokines (TNF-α, IL-1β, IL-6, and IFN-γ), and monocyte chemoattractant protein-1 (MCP-1)." (PMID 37383542, 2023). "Indeed, IRX3 expression in adipocytes negatively correlated with obesity-related parameters of AT dysfunction, i.e. adipocyte diameter and AT inflammation as indicated by the number of infiltrating macrophages and CD68 mRNA expression in the SVF." (PMID 27560134, 2016).
Obesity (continued). "However, according to available data, CLS density of greater omentum fat tissue is much less pronounced compared to other visceral and subcutaneous fat tissue depots, and this probably makes the CD68 expression data obtained by us in patients with different obesity phenotypes more tenable." (PMID 27853670, 2016). "However, we observed greater CD68 cell counts were associated with advanced tumor grade, regardless of obesity status (p = 0.019)." (PMID 27487262, 2016). "For CD68, two-way ANOVA revealed significant effects of obesity (F = 108.4; p < 0.0001), OEA-DS application (F = 21.68; p < 0.0001), and a significant interaction effect of these factors (F = 26.07; p < 0.0001)." (PMID 40265441, 2025). "In the present study, we found that hypertrophic adipocytes from patients with lipedema, mainly in affected areas, were infiltrated by CD68 macrophages, but CLS, quite frequently observed in patients with obesity, were rare." (PMID 40077894, 2025). "From an immune cell perspective, independent associations within the tumor compartment were observed for iCCA (myosteatosis: TIM-3+CD8+cells; obesity: PD-1+TIM-3+CD4+cells) and for pCCA (myosteatosis: PD-L2+CD68-cells and CD4+cells)." (PMID 39760117, 2024). "Further analysis of the myeloid cell clusters revealed the presence of four transcriptionally distinct CD68+ liver myeloid cell subpopulations (LM1–LM4) in both lean individuals and individuals with obesity." (PMID 37414931, 2023). "Thus, our results show that the association between obesity and vitamin D deficiency contributed to an exacerbation of the inflammatory process observed in the HFDV group, which had higher expression of MCP-1 and CD3+ cells and a lower proportion of CD206+ cells in relation to the CD68+ cells." (PMID 36466412, 2022). "A significant decrease in pro-inflammatory macrophages markers (mRNA levels of iNOS (P < 0.05), CD68 (P < 0.05), CD163 (P < 0.05)) was found within the subcutaneous AT of our IR subjects with obesity." (PMID 33753887, 2021). "The remarkably elevated expression of CD68 and F4/80 in obese mice demonstrated increased infiltration of macrophages in WAT during dietary obesity, which was suppressed by hASCs infusion." (PMID 34222665, 2021). "In this study, CD68 and EMR-1 expressions in the SS group were elevated, suggesting that sepsis concomitant with obesity did increase macrophage infiltration and exaggerate inflammation of adipose tissues." (PMID 33223959, 2020). "Similarly, apabetalone differentially reduced gene expression of the phagocytic macrophage receptor CD68, of the IL-10 receptor subunit IL10RB implicated in pro- and anti-inflammatory homeostasis, and of MTMR14 encoding a phosphoinositide phosphatase involved in metabolic dysregulation in obesity." (PMID 33172487, 2020). "CD68/CD11C macrophages (M1) were dramatically decreased in in tissue from the EA or Resveratrol group, as compared to those from Obesity group." (PMID 30425749, 2018). "In the murine model of obesity, the expression level of inflammatory markers including IL-1β and TNF-α as well as the macrophage marker CD68 was significantly enhanced in metabolic organs, together with CypB." (PMID 29312150, 2017). "Similarly, in obesity, collagen VI expression in omental white adipose tissue is correlated with expression of MCP-1, CD68, and CD86, providing further evidence that this collagen influences macrophage infiltration and phenotype." (PMID 36901727, 2023). "CD206 expression was similar between the obese and obese-diabetic groups, but the women with obesity-diabetes had higher expression levels of CD11c and CD68 than their obese counterparts without diabetes." (PMID 35933445, 2022). "Exposure to obesity, maternal obesity or gestational hydralazine did not alter renal CD68 mRNA expression." (PMID 34485290, 2021).
Obesity (continued). "Low Cd68 expression in eWAT, an inflammatory marker, gives a first insight regarding a low inflammatory state within the adipose tissue in the presence of HFD‐WPI, which is usually very high in mice and humans with obesity." (PMID 32748559, 2020). "At the end of the 12‐week obesity induction period, soleus fat content, connective tissue content, and CD68+ cell number, were similar across all groups, regardless of diet or obesity response (P > 0.05)." (PMID 28533262, 2017). "CD68 protein expression was increased by maternal obesity regardless of offspring diet (HC vs. CC, p < 0.01 and HH vs. CC p < 0.0001 respectively)." (PMID 27004609, 2016). "Additionally, a direct correlation between BMI and gene expression was observed for AGER, ANGPT2, CD68, IFI30, NOTCH3 and SPP1, whereas an inverse correlation was achieved for DLL4, PLIN, PNPLA2 and VEGF (genes that were down-regulated due to obesity)." (PMID 33022994, 2020). "However, according to our findings, no connection was identified in literature between the level of CD68-labelled macrophages and obesity in patients without any metabolic disorder." (PMID 26101731, 2015). "Furthermore, HFD-induced obesity contributes to microglial reactivity in the hippocampus of C57BL/6J mice, as evidenced by an increase in the microglial soma area (without significant cell proliferation) along with the increased co-localization of Iba-1 and CD68 markers." (PMID 35252286, 2022). "Although we could not identify the underlying mechanism or the link among resistin, leptin, and CD163/CD68 expression levels, our data suggest that serum resistin levels and leptin levels have specific roles in the regulation of ATM in patients with modest obesity." (PMID 27101398, 2016). "Quantification of immunofluorescent staining of recently recruited (CD68+S100A9+) myeloid cells did not reveal any significant differences in monocyte recruitment between lean individuals and individuals with obesity." (PMID 37414931, 2023). "Increased hepatic expression of Gpr119 and Cd68, but not Cnr1 was also detected in mice with CL-HFS-induced NASH and human patients with obesity and NASH." (PMID 36646715, 2023). "In the independent validation, cohort 1 of n = 32 patients with obesity whose VAT gene expression was assessed by microarrays, all MC genes probe sets (KIT, TPSB2, CMA1) exhibited significant negative correlations with macrophage gene probes (CD68, Mac2, IGTAX(CD11c))." (PMID 32575785, 2020).
Stroke (81 papers, 2010 to 2026). Sudden impairment of blood flow to a part of the brain due to occlusion or rupture of an artery to the brain. "In contrast to the limited effects of minocycline on the measures of Iba1-immunolabeling in peri-infarct tissue, there was a marked reduction at 3 days after stroke induction in cells expressing CD68, a protein usually associated with microglia and macrophages that are involved in phagocytosis." (PMID 30626393, 2019). "The current study is the first to show that phagocytic cells may play a dual role after stroke since the most prominent protection observed 3 days after the insult was associated with increased CD-68 expression." (PMID 21627837, 2011). "In contrast, distal MCAO mice treated with a miR-155 inhibitor 48 h post-stroke exhibited decreased expression of CD68, a phagocytic marker, in peri-vascular microglia and macrophages." (PMID 40766256, 2025). "We found more CD68+/SYP+ cells in the peri-atrophic region of old stroke mice than young stroke mice (p=0.045); in the ipsilateral side than the contralateral side of the hippocampi in the old stroke mice (p=0.035)." (PMID 40661422, 2025). "The old stroke mice also had more CD68+/SYP+ cells in the ipsilateral side of the hippocampi than in young stroke mice (p=0.042)." (PMID 40661422, 2025). "This is supported by a previous study in a model of adult stroke, which revealed increased transforming growth factor beta expression, specifically in CD68+ microglia." (PMID 40136692, 2025). "In stroke models, the presence of CD31 granules and other endothelial markers correlates with CD68 phagosomes in perivascular microglia, suggesting that microglia phagocytose endothelial cells post‐stroke, contributing to BBB disruption." (PMID 41367136, 2025). "Clinical studies have shown a significant increase in the number of penumbral AIM2+/CD68+ cells in stroke patients." (PMID 40351418, 2025). "In young female mice subjected to dMCAO, the TGFβ1 protein predominantly co-localized with CD68, activated microglia and macrophages, at 3 days post-stroke." (PMID 40667795, 2025). "MANF and CD68 positive signals were found to be co-localized in the same cells in the post-stroke rat brain verified by confocal microscopy." (PMID 38229173, 2024). "Eng+/− mice showed fewer CD68+ cells in the peri-infarct area at 3 days but more at 60 days after stroke injury in mouse." (PMID 39200156, 2024). "In stroke groups, CD68 was significantly increased in the microglia from Kdm6afl/fl vs. fl/y mice, and Kdm5cfl/fl mice had significantly higher CD68 than either fl/y or CKO mice." (PMID 39399684, 2024). "Contributing to the animal model findings, a study in stroke patients indicated an increase in 18F-fluorocholine (18F-FCH) uptake in the affected carotid plaques that correlated with CD68+ cells in the endarterectomy biopsies of the same patients." (PMID 39594602, 2024). "Our study yielded similar results, a strong presence of CD68 was evident in the whole AH as early as 3 days after stroke and it was significantly higher in the Rexed's lamina IX compared to the entire AH." (PMID 38082027, 2023). "In all stroke time points, CD68 intensity in CD11c- microglia was only half of that in CD11c+ microglia." (PMID 36828819, 2023). "In our previous study, MANF, a paralogous protein of CDNF, was shown to increase the density of ARG1+ and CD68+ cells in subcortical regions after stroke." (PMID 36792604, 2023). "Together with GFAP staining, these data suggest that in the absence of TIC cytokines, minimal differences occur in astrocyte GFAP and myeloid cell CD68 protein levels immediately following stroke." (PMID 38240014, 2023). "To examine how TIC cytokines collectively influence myeloid cells following ischemic stroke, we used CD68+ immunostaining and quantified cell coverage in the peri-infarct at 24 h, and 7 days following dMCAO, and 30 days after photothrombotic stroke." (PMID 38240014, 2023).
Stroke (continued). "This likely was too late, since the post-stroke neuroinflammatory response was probably already in its descending phase, as also suggested by the CD68 data, showing that the number of these cells was unaffected at this time point." (PMID 36835405, 2023). "CD68, a marker of microglia phagocytic activity, peaks and invades the ischemic core at 7d after stroke onset." (PMID 37270727, 2023). "Further, microglia numbers, pro-inflammatory morphology and expression of CD68 were also reduced after neonatal H-I when metformin treatment was delayed post-stroke." (PMID 35705953, 2022). "Our results showed that MFI of CD68 was significantly downregulated in IRF5 CKO vs. flox mice after stroke; meanwhile CD206 was significantly upregulated by IRF5 CKO." (PMID 35963621, 2022). "Herein, we show that the microglia response is regionally distinct at early times post-stroke and metformin treatment reduces microglia activation, as measured by morphology and protein expression (CD68)." (PMID 35705953, 2022). "Post‐stroke patients who develop dementia accrued more perivascular activated CD68+ microglia in the frontal white matter (FWM)." (PMID 35748290, 2022). "Immunostaining in adjacent brain sections demonstrated localized increase in CD68 + microglia in the stroke region after MCAo, corresponding to the elevated autoradiography signal." (PMID 36279013, 2022). "Higher total density of CD68+ microglial cells was detected in the frontal WM compared to the overlying cortex not only in the post‐stroke subjects, but also in the age‐matched controls, consistent with previous reports." (PMID 35748290, 2022). "We observed marked differences between WT and CD36 KO of multiple well-described inflammatory players in neonatal stroke and hypoxia–ischemia, including down-regulation of Tlr4, Timp1, Csf-1 and CD68." (PMID 35148760, 2022). "To further confirm these results, we performed the IF staining, which showed that stroke resulted in a significant increase in CD68+ and iNOS+ cells in Sult2b1-/- mice." (PMID 34815805, 2021). "CD68 is a protein produced by subpopulations of Iba1-positive cells within the first few days of stroke induction." (PMID 34332596, 2021). "Within the first few days after stroke induction, CD68-positive cells are found in outer parts of the infarct, with smaller numbers in the peri-infarct tissue immediately adjacent to the lesion." (PMID 34332596, 2021). "CORT administration after stroke was observed to reduce the expression of CD68 approximately threefold compared to the stroke-alone condition (stroke = 64.3% vs. stroke + CORT = 25.84%, p < 0.05)." (PMID 34206635, 2021). "At 3 days post-stroke, CD68+ cells can be seen in the periphery of the stroke lesion and this continues for several weeks post-stroke concomitant with the formation of a glial scar." (PMID 33082455, 2020). "We found Eng+/− mice had fewer cluster of cluster of differentiation 68+ (CD68+) microglia/macrophages 3 days after ischemic stroke and more CD68+ microglia/macrophages 60 days after stroke in the peri-infarct areas." (PMID 32954380, 2020). "Multiple comparisons with Tukey’s post-hoc correction indicated that compared to the sham group (290 ± 17.6 cells/mm2), the stroke (381 ± 26.1, p = 0.007) and BF+stroke (437 ± 45.3, p < 0.001) groups had more CD68+ cells." (PMID 33187248, 2020). "In our previous studies, we reported that CD68+ microglia express IGF-1 in the brain of a stroke model." (PMID 32952570, 2020). "The stroke (p = 0.004) and BF+stroke (p < 0.001) mice had more CD68+ cells than BF mice (310 ± 21.2)." (PMID 33187248, 2020). "Our results show that SND was associated with a considerable change in microglial morphology as well as enhanced expression of CD68, a putative marker of phagocytosis and CD11b a putative marker of complement recognition at day 15 post stroke." (PMID 30890719, 2019).